ERBB2 (erb-b2 receptor tyrosine kinase 2)
Diseases named in the same sentence as ERBB2 in open-access papers (continued):
Sharing a sentence is not in itself a finding about the gene and the disease.
cancer (continued). "The epidermal growth factor receptor (EGFR) family of receptor tyrosine kinases, which consists of EGFR, ErbB2, ErbB3, and ErbB4, is important in many normal developmental processes and is often over-expressed or mutated in human cancer." (PMID 19019207, 2008). "Inappropriate signalling through the EGFR and ErbB2/HER2 members of the epidermal growth factor family of receptor tyrosine kinases is well recognised as being causally linked to a variety of cancers." (PMID 18841159, 2008). "Grb7 is an especially promising cancer target as the encoding gene maps closely to the ErbB2 gene on human chromosome 17q12 and is found co-amplified and overexpressed in a subset of breast, esophageal and gastric cancers." (PMID 17426702, 2007). "We demonstrate that the genomic mechanisms of ERBB2 activation—inclusive of amplification, mutation, and rare intragenic rearrangements—vary across cancers and that this diverse spectrum of activating alteration types is detectable through CGP of both tissue and liquid biopsies." (PMID 40178042, 2025). "Moreover, these two SBS subtypes differed in somatic mutations in several cancer driver genes, including higher mutation frequency of ERBB2, GATA3 and FGFR4, and lower frequency of DMD, INHBA, OGDHL, PLEKHG5 and RYR2 in subtype 3 than in subtype 1 (P < 0.05)." (PMID 40858906, 2025). "However, similar to other cancers, ERBB2 mutations/amplifications appear to be poor prognostic factors for CCA." (PMID 41008893, 2025). "Our future research will focus on developing monoclonal neutralizing antibodies and ADCs targeting ERBB2 i14e and investigate the role of this isoform in other ERBB2 associated cancer types, ultimately enhancing the efficacy of trastuzumab-based regimens for ERBB2 i14e-expressing cancers." (PMID 39948369, 2025). "However, other aberrant variations of ERBB2 exist in human cancer, including ERBB2 oncogenic variants found in 3.5% of solid tumors, with varying prevalence across cancer types." (PMID 40770324, 2025). "Most studies on ERBB2 polymorphisms focus on their association with cancer." (PMID 40564170, 2025). "In conclusion, we have identified many new susceptibility genes for ERBB2-driven cancer." (PMID 39067134, 2024). "Therefore, the search for ERBB2 mutations will become part of the standard management of breast and other cancers, as ERBB2 mutations are found across multiple cancers (e.g., uterine, cervical, colorectal, and lung)." (PMID 38287892, 2024). "Our investigation has unveiled many new genes predisposing individuals to ERBB2-driven cancer." (PMID 39067134, 2024). "Importantly, ErbB2 (also known as Her2) is a prominent oncogene and ErbB1/ErbB2 dysregulation or amplification is associated with poor prognosis in several cancer types." (PMID 39426288, 2024). "In the reported data in Western populations (cBioPortal and MDACC), ERBB2 mutations were most commonly observed in the tyrosine kinase domain (46%), with mutations in exon 20 (20%), exon 19 (11%), and exon 21 (9%) across all cancers." (PMID 39220126, 2024). "In ERBB2-mutated cancers, the benefit of anti-HER2 TKIs has been evaluated." (PMID 36980614, 2023). "Notably, high-level ERBB2/HER2 expression was associated with increased cancer mortality and significantly worse overall survival (OS) of MM patients." (PMID 37373090, 2023). "Furthermore, Dmel\ EGFR is orthologous to human gene ERBB2, which has also been implicated in multiple cancers." (PMID 36926584, 2023).
cancer (continued). "Our results encourage further evaluation of the prognostic significance of high-level ERBB2 mRNA expression and the clinical potential of ERBB2-targeting therapeutics as personalized medicines to overcome cancer drug resistance in high-risk as well as relapsed/refractory MM." (PMID 37373090, 2023). "Since CREB1 functions in cancer signaling, together with data on the involvement of ABL1 and ERBB2 protein kinases in pathways in cancers, it suggests the presence of upstream cancer-associated tissue-specific transcriptional regulation in DLBC and THYM cancers." (PMID 37373333, 2023). "The NCDB includes only OS data, which limits associations of ERBB2-low status with cancer-specific prognosis, especially in the hormone receptor–positive cohort, where survival may lag years behind recurrence." (PMID 36821125, 2023). "In addition, compared to the results presented, patients with ERBB2 overexpression had an increased risk of death, particularly of cancer-specific death." (PMID 37173881, 2023). "In addition, drug susceptibility of cancer varies with ERBB2 mutations, and identifying individual ERBB2 mutations to develop effective targeted treatments is difficult." (PMID 37754252, 2023). "Intracellular hTid-1 interacts with the ErbB2 signaling domain, causing its proteasomal degradation via polyubiquitination, thereby helping in the attenuation of mitogenic signaling from ErbB2 in cancer cells." (PMID 35854300, 2022). "Whether immunotherapy can be used in other cancers carrying ERBB2 mutations/amplifications need further exploration." (PMID 35911441, 2022). "As found previously, ERBB2 was implicated in the development of human cancers." (PMID 35524932, 2022). "We demonstrated that over-expression of ERBB2 was associated with a poor prognosis for cancers." (PMID 36172165, 2022). "To assess the role of different pathways and cancer hallmark genes in therapeutic responses of drugs we have set up a machine learning-based ranking and validation and utilized this feature to evaluate genes related to anti-ERBB2 therapy resistance." (PMID 35765648, 2022). "Moreover, in contrast to ERBB2 kinase domain variants, there are few studies dealing with the mechanisms by which ERBB2 ECD variants activate certain cellular processes related to cancer." (PMID 34997908, 2022). "Preclinical data indicates that ERBB2 mutations may confer a sensitivity to HER2-targeted drugs and that activating HER2 mutations may drive cancer progression similarly to ERBB2 amplification." (PMID 35181666, 2022). "ERBB2 amplification and mutation have been identified in many cancer types." (PMID 36425071, 2022). "ERBB2 mutations are also found in other common cancers, including lung and colorectal." (PMID 36276102, 2022). "We selected the ERBB2 gene for further studies, which encodes the epidermal growth factor receptor that was previously found to be involved in the tumorigenesis of many different types of cancers." (PMID 35524932, 2022). "Cancers overexpressing the ERBB2 oncogene are aggressive and associated with a poor prognosis." (PMID 33809102, 2021). "In conclusion, p140Cap expression is associated with reduced risk of metastasis (and death from cancer), in the ERBB2-amplified subgroup of BCs, suggesting a possible role of p140Cap in counteracting the migratory and/or metastatic ability of ERBB2-amplified cancer cells." (PMID 33079227, 2021). "ErbB2 plays roles in cell proliferation, survival, and differentiation in vitro and in vivo, and its upregulation by the gene amplification causes many types of cancers, including breast and gastric cancers." (PMID 33795719, 2021). "Mutations in the ERBB2 kinase domain have been identified in about 2–5% of various human cancers." (PMID 34396843, 2021).
cancer (continued). "Human epidermal growth factor 2 (HER2/ERBB2) is frequently amplified/mutated in cancer." (PMID 33473169, 2021). "Accordingly, we constructed a PPI network centered around CHN1 as the core gene and found an association between the expression of CHN1 and ERBB2, which is involved in the pathogenesis and adverse consequences of various cancers, including terminal GC and gastro-esophageal junction cancer." (PMID 34152250, 2021). "Two α2,3NeuAc-recognizing molecules were used: the Maackia amurensis lectin II (MAL-II), which harbors affinity towards α2,3NeuAc-containing glycan epitopes; and the CA-19.9 mAb, which recognizes the cancer-associated SLea antigen, previously shown to be carried by ErbB2." (PMID 33947960, 2021). "However, only lapatinib targets cancers that overexpress ERBB2/HER2; erlotinib and gefitinib act in cancers with mutated or overactive EGFR." (PMID 32366937, 2020). "Clinically, ERBB2 mutation had become an important target for cancer therapy." (PMID 32780567, 2020). "Similarly, gene expression changes associated with breast EMT and cancer progression were detected, as the reduction of ERa and ERBB2 and the increase of NOTCH1 and WNT5B." (PMID 32699630, 2020). "Predicted genes include TGFβR2, PTEN and ERBB2 which are often mutated in cancer." (PMID 32141232, 2020). "It is worth noting that in cancer cells, the activation of ERBB2 is often associated with amplification and overexpression of ERBB2, in which the crowding of the receptor may be localized to specific regions of the cell." (PMID 31333463, 2019). "The anti-cancer effect exerted by GroA led us to examine whether it was, in fact, caused by the disruption of the ErbB2–nucleolin interaction." (PMID 29352243, 2018). "Similarly to EGFR, HER2, encoded by the ERBB2 gene, is also often overexpressed in cancer and its deregulation is associated with aggressive phenotype and shortened survival." (PMID 29455660, 2018). "EGFR (in KEGG, Reactome, and WikiPathway) and ErbB2 (in Reactome) are reported to be frequently mutated and/or over-expressed in various types of cancer resulting in aberrant activities contributing to abnormal cell growth, survival, migration, and differentiation." (PMID 28288164, 2017). "Additionally, African women displayed a notably higher risk of having cancers harbouring ERBB2 mutations (HR: 8.01; 95% CL: 2.41-26.68; p=0.001), and a lower risk of KRAS mutations (HR: 0.34; 95% CL: 0.13-0.89; p=0.027)." (PMID 28881604, 2017). "Moreover, the inhibitory effect of lapatinib on EGFR/ErbB2 signaling in the sensitive condition was found to be associated with glucose starvation of cancer cells, and thus induced cancer cell death." (PMID 28288164, 2017). "Five-point-five percent 5.5% of these patients displayed somatic alterations classified as 2b, defined as an approved biomarker in another cancer indication and included ERBB2 amplifications, CDK4 amplifications, BRCA1/2 mutations, BRAFV600E mutation and fusion events involving ROS1 and ALK1." (PMID 29156578, 2017). "The erythroblastosis oncogene B (ErbB) receptors such as epidermal growth factor receptor (EGFR/ErbB1/HER1) and ErbB2, also known as HER2 or p185c-neu, are implicated and overexpressed in the development of many types of cancer, and undergo several alterations in human cancers." (PMID 29050225, 2017). "ErbB2 gene amplification in cancer causes constitutive signaling." (PMID 27175488, 2016). "Thus, both p-ErbB2 and p-ErbB3 are—despite their mutual interdependence—individually contributing to the survival of treated cancer cells by causing reactivation of AKT." (PMID 27255951, 2016). "Activation of the ErbB2/ErbB3 signaling unit via overexpression of the receptors, gain-of-function oncogenic mutations, or autocrine release of the ErbB3 ligand, heregulin, have been identified in many types of cancer." (PMID 27570763, 2016).
cancer (continued). "In addition, MUC4 has also been implicated in cancer by mediating the epidermal growth factor family of enzymes, including the tyrosine kinase receptor ERBB2." (PMID 26686060, 2015). "In addition to amplification and overexpression, mutations in ERBB2 have been reported in multiple cancer types, including UC, and are oncogenic in vitro 5–8." (PMID 25720673, 2015). "Exploration of recurrent alterations in the branches of carcinoma-specific mutations with distinct mutational contexts such as ERBB2 amplification preceding APC and KRAS mutations would also be valuable information for understanding the evolutionary process of CRC." (PMID 26336987, 2015). "The physical association of ErbB1 with c-Met, ErbB2, or ErbB3 expands the network of signaling pathways that are activated in cancer cells and illustrates why a single tyrosine kinase inhibitor may not be sufficient to eradicate disease." (PMID 23866081, 2013). "Thus far, we focused our review on preclinical and clinical studies evaluating the existing anti-ERBB2 agents on cancers harboring activating mutations of ERBB2 as single agents with or without adjacent chemotherapy." (PMID 23630663, 2013). "Results presented in this manuscript, taken together with previously published results, demonstrate that loss of polarity proteins efficiently cooperate with ErbB2 to induce invasion and suggest that dysregulation of polarity proteins can regulate metastatic progression of ErbB2 positive cancers." (PMID 22529912, 2012). "Another indel, the five nucleotide deletion rs138461304 in the seed region of miR-559, may disrupt targeting of ERBB2 by miR-559, resulting in overexpression of ERBB2, an abnormality that has been associated with cancer." (PMID 23049969, 2012). "Besides the fact that the ErbB receptors are indispensable during development and in normal adult physiology, epidermal growth factor (EGFR) and ErbB2 in particular have been implicated in the development of many human cancers." (PMID 23202898, 2012). "According to previous reports on MIBC, erbB2 overexpression is an independent risk factor for cancer death in patients undergoing radical cystectomy and an independent predictor of non-CR after CRT but not a risk factor for cancer death in patients treated with CRT." (PMID 22102915, 2011). "Anthracyclines and the human ERBB2 monoclonal antibody (trastuzumab) are the two anti-cancer drugs associated with the highest cardiotoxicity risk, at times causing LV dysfunction and symptomatic HF, collectively termed cancer therapy-related cardiac dysfunction (CTRCD)." (PMID 39953627, 2025). "Finally, we found a decreased ERBB2 expression in carcinomas with an activating PIK3CA mutation." (PMID 38893129, 2024). "Besides CSE1L upregulation, other cancers may subvert the acute effects of nuclear ERBB2 directly by mutation." (PMID 37055441, 2023). "Additionally, we analyzed 28 cancer-associated genetic variants with ERBB2 mutations." (PMID 37754252, 2023). "Indeed, increased ErbB2 expression has been associated with drug resistance in cancer cells." (PMID 35372019, 2022). "Aberrant signaling by EGFR (ErbB1) and ErbB2, caused by gene amplification, deletions in the extracellular domain, activating kinase domain mutations, or ligand coexpression, drives the progression of many human cancers, especially in the breast, lungs, and colon." (PMID 34572289, 2021). "Additionally, the human GRB7 gene is located on chromosome 17q12, in close proximity to the cancer-associated ERBB2 gene, which has been identified as an ERBB2 amplicon, suggesting the coamplification and coexpression of Grb7 and ERBB2 contribute to cancer development." (PMID 31083325, 2019). "Importantly, cancers with ERBB2 mutations could be treated by Neratinib, an irreversible pan-HER tyrosine kinase inhibitor, which is currently in late-phase clinical development." (PMID 27811364, 2016).
cancer (continued). "However, DOX enhances the cardiotoxicity associated with ErbB2-targeted antibody therapeutics, including Trastuzumab, and as such the approach will need modifications to incorporate drugs more appropriate for ErbB2+ cancer therapy." (PMID 26859680, 2016). "Additionally, our research on the l11Jus8 mutant may inform future investigations into chemotherapy-induced cardiotoxicity associated with inhibition of ERBB2 signalling, as new anti-cancer therapeutics are being designed to target the ERBB2 kinase domain." (PMID 25269082, 2014). "We show that inhibition of the ErbB2-Par6 pathway was sufficient to block ErbB2-induced invasion, even in the presence of the second polarity gene loss, suggesting that developing ways to inhibit the ErbB2-Par6/aPKC pathway will open new avenues for blocking metastasis in ErbB2 positive cancers." (PMID 22529912, 2012). "Overexpression of the human epidermal growth factor receptor 2 (ERBB2(HER2)), also known as C-erbB-2, can lead to the activation of cellular signal transduction systems, resulting in the cellular transformation and cell proliferation events associated with cancer." (PMID 21689422, 2011). "We demonstrated this modularity by equipping the vector withdifferent SpyCatcher-DARPin fusion proteins specific for EGFR, EpCAM,and HER2/ErbB2, thereby achieving efficient and specific transductionof corresponding cancer cell lines." (PMID 41430475, 2026). "MI Cancer Seek results for ERBB2 CNAs were compared to results of the PathVysion HER2 DNA Probe Kit, yielding 84.7% PPA and 99.4% NPA." (PMID 40804002, 2025). "Amplification of the ERBB2 gene results in up to a 100-fold increase in HER2 receptor expression on the surface of cancer cells compared to normal mammary cells." (PMID 40563575, 2025). "On the one hand, the interesting gene list contains many cancer genes, such as ERBB2, HMGA1, and MET, that are related to these cancer types, which have been widely studied." (PMID 40139908, 2025). "ERBB2 gene amplification and mutation are generally mutually exclusive, suggesting that they are independent oncogenic drivers of tumorigenesis, and these alterations may be responsible for the different oncogenesis, biological properties, and clinical features of various cancers." (PMID 41154672, 2025). "For ERBB2-Positive (HER2/ERBB2+) cancers, treatments targeting HER2 protein (such as Trastuzumab and Pertuzumab) are combined with chemotherapy." (PMID 40136435, 2025). "This variant considerably facilitated the interaction between ERBB2 and ERBB3 and triggered stronger downstream signaling cascade than the wild type ERBB2 to promote cancer cell proliferation." (PMID 39948369, 2025). "Efficacy was assessed in human ErbB2+ RMS cancer cell lines and primary patient samples in vitro and ex vivo using cytotoxicity and spheroid co-incubation assays." (PMID 39963129, 2025). "The overexpression of NRG1 can activate the ERBB3/ERBB2-signaling pathway, promoting cancer cell proliferation, invasion, and metastasis." (PMID 41378303, 2025). "We classified patients by levels of Tob expression and NF-κB activation into the following cancer subtypes: basal-like, claudin-low, ErbB2 positive, luminal-like, and unclassified." (PMID 40169858, 2025). "The multiplex approach was compared between two assay chemistries, applied to healthy donor genomic DNA and plasma cell-free DNA (cfDNA) to measure the ERBB2 (HER2) copy number variation in cancer cell line DNA." (PMID 41090772, 2025). "NGS targeting 54 cancer related genes, including assessments for copy number variants in EGFR, ERBB2, and MET." (PMID 40867329, 2025). "The sashimi plots derived from four independent GBC cohorts showed that ERBB2 i14e was elevated in cancer." (PMID 39948369, 2025). "Numerous studies show that ERBB2 can regulate the proliferation and invasion of cancer cells by modulating the PI3K/AKT pathway." (PMID 41305721, 2025).